PSMB8 (proteasome 20S subunit beta 8)
Diseases named in the same sentence as PSMB8 in open-access papers (continued):
Sharing a sentence is not in itself a finding about the gene and the disease.
multiple myeloma (10 papers, 2017 to 2025). "LMP7 (β5i/PSMB8), a proteolytic subunit of the immunoproteasome, is implicated in the pathogenesis of multiple myeloma, autoimmune and inflammatory diseases, and inflammation-related cancers." (PMID 40507366, 2025). "The resistance to inhibitor bortezomib was also found to be associated with mutation in the PSMB8 gene loci in multiple myeloma, which further potentiates the significance of screening PSMB8 mutations as well as expression for detecting chemoresistance to therapy." (PMID 34944095, 2021). "Recently, M3258 was synthesized using the α-aminoboronic acid scaffold as a starting point to optimize selectivity for PSMB8 (> 500fold over PSMB5) and has entered early clinical trials for multiple myeloma." (PMID 38049829, 2023). "PSMB8 and PSMB9 are the targets of Carfilzomib, a proteasome inhibitor for multiple myeloma." (PMID 29321020, 2018). "In patient-derived myeloma cell lines that were engineered to constitutively express mutant forms of either KRAS, NRAS or BRAF, the expression of each of these oncogenes increased the transcription of proteasome 20S subunit beta 8, 9 and 10 (PSMB8, PSMB9 and PSMB10)." (PMID 35147163, 2022).
Autoimmunity (8 papers, 2014 to 2025). The occurrence of an immune reaction against the organism's own cells or tissues. "A deficiency in β5i encoded by PSMB8 can lead to autoimmunity and affect the T cell lineage differentiation." (PMID 28081217, 2017). "Studies in PSMB8/-9 deficienct mice suggested that inflammation induced immunoproteasome expression in tissue may also prevent CD8+ T-cell mediated autoimmunity." (PMID 25098831, 2014).
colorectal cancer (8 papers, 2017 to 2025). A primary or metastatic malignant neoplasm that affects the colon or rectum. "The PSMB1-7 were essential for most colorectal cancer cell lines, while only few cell lines dependent on expression of immune subunits PSMB8-10." (PMID 38774235, 2024). "Abnormal methylation of PSMB8 has been reported in ovarian, breast, and colorectal cancers." (PMID 41132793, 2025). "The downregulation of PSMB8.AS1 repressed cell viability and EMT of colorectal cancer while promoting its apoptosis." (PMID 36739404, 2023). "Genetic polymorphism in PSMB8 (LMP7, PSMB5i, β5i) has also been described in colorectal cancer patients associated with reduced inducibility in response to IFN-γ, another potential mechanism by which colorectal cancer cells may be able to escape immune surveillance." (PMID 32850906, 2020).
COVID-19 (8 papers, 2020 to 2024). A disease caused by infection with severe acute respiratory syndrome coronavirus 2. "We observed the distinct association between “severe COVID-19 or rheumatoid arthritis” with JIA that was mediated by a subset of 6p21.3 genes within cluster 8 (AGPAT1, PSMB8, TAP1, HCG4P11, HLA-DMB)." (PMID 39175752, 2024). "In mild cases of COVID-19, we further observed that the expression of PSMB8 in alveolar monocytes/macrophages was correlated with that of genes associated with the polarization of M1 macrophages, such as CD68, MYD88, and STAT1." (PMID 34225749, 2021). "Further investigation of single-cell heterogeneity in bronchoalveolar cells revealed a cell trajectory in M1 macrophages during mild cases of COVID-19 that is shaped by expression of the PSMB8 subunit of the immunoproteasome." (PMID 34225749, 2021). "In the resulting pseudotime transformation of cell development, branch number 3 appears to differentiate between cells with low expression of PSMB8 (i.e. severe COVID-19) from those with medium and high levels of PSMB8 (mild COVID-19)." (PMID 34225749, 2021). "By investigating the PSMB8 subunit of the immunoproteasome, we identified single-cell heterogeneity in the expression of this gene that revealed a cell trajectory for alveolar M1 macrophages during mild stages of COVID-19." (PMID 34225749, 2021). "Furthermore, in patients with mild COVID-19, the high expression of PSMB8 could promote M1 macrophage polarization." (PMID 37007947, 2023). "In lung endothelial cells, the PSMB8 (ENSG00000204264) gene was found to be upregulated in controls and downregulated in samples receiving two doses of attenuated COVID-19 vaccines based on our rule." (PMID 37007947, 2023). "Specifically, along with CD68, the immunoproteasome-related genes PSMB8, TAP1, PSMB9, PSMB10, and calreticulin (CALR) were all found to be expressed in the CD14+/CD16+ subpopulation of cells during mild COVID-19." (PMID 34225749, 2021). "Similarly, in the trajectory signature for alveolar macrophages from mild COVID-19 patients, CALR, MARCO and TNFSF13 followed the expression patterns of CD68 and PSMB8." (PMID 34225749, 2021). "Moreover, PSMB1, PSMB4, PSMB8 were not overexpressed in COVID-19 patients PBMCs." (PMID 35327634, 2022).
breast carcinoma (7 papers, 2017 to 2025). "This has been very well studied in breast cancer for which PSMB8 expression was linked to better disease-free survival in patients presenting with lymph node metastases at the time of diagnosis." (PMID 40698074, 2025). "In human breast cancer, high PSMB8 expression was associated with increased intra-tumoral CD8 T cell infiltration." (PMID 40698074, 2025). "Along these lines, it has been shown that Ki-67 knockout breast cancer cells demonstrate decreased expression of PSMB8 and PSMB9." (PMID 39796785, 2025). "In breast cancer, retinoic acid receptor responder protein 3, a known suppressor of lung metastasis, has been shown to downregulate PSMB8, 9 and 10 expression through IRF1 depletion." (PMID 40698074, 2025). "In breast cancer, PSMB8, 9 and 10 have been found to be expressed to higher levels in hormone-positive cancers compared to other subtypes." (PMID 40698074, 2025). "The TCGA-BRCA breast cancer dataset exhibits separate Kaplan–Meier survival curves (KM) for four notable genes (PSMB8, BCL2, BMP5, and PSME2)." (PMID 41403941, 2025). "Next, we wanted to determine if the samples that contained more PSMB8 + cells also contained more PSMB9 + cells and found a strong correlative association for all breast cancer subtypes together, as well as for TNBC specifically." (PMID 36746983, 2023). "In order to determine the impact of ImP expression on breast cancer outcomes, we assessed the protein expression and cellular source of the ImP subunits PSMB8 and PSMB9 in a cohort of 2070 patients." (PMID 36746983, 2023). "Considering that PSMB8 knockdown/knockout reduces proliferation of some breast cancer cell lines, immunoproteasome expression in cancer cells may play an important role in BC carcinogenesis." (PMID 39796785, 2025). "Thus, our results indicate that breast cancer types differ in terms of proteasome subunit expression pattern, and together with strong PSMB8-10 co-correlation in tumors, these data suggest exclusive function of immunoproteasomes in biology of the BC." (PMID 39796785, 2025). "In breast cancer patient samples, PSMB8 was shown to be decreased in brain metastases, suggesting that its loss could play a role in metastasis." (PMID 40698074, 2025). "To investigate if the revealed differences in gene expression correlate with the amount of proteasome subunits in cancer cells, we analyzed the relative levels of mRNAs encoding the immunoproteasome subunits PSMB8, PSMB9 and PSMB10 in four breast cancer cell lines: MCF-7, SKBR3, ZR-75-1 and BT-474." (PMID 39796785, 2025). "We therefore considered that the relationship between RARRES3 and PSMB8 might provide insights into immune modulatory mechanism in breast cancer." (PMID 28051153, 2017). "We examined the clinical correlation of four key genes (PSMB8, BCL2, BMP5, and PSME2) with breast cancer prognosis." (PMID 41403941, 2025). "We used the IMMUcan database to analyze single-cell RNA data and examine the expression of PSMB8, BCL2, and PSME2 in the breast cancer immune microenvironment." (PMID 41403941, 2025). "Here, we sought to determine the impact of PSMB8 and PSMB9 expression at the protein level on outcomes in breast cancer and TNBC patients, but also in the context of the cell type expressing the ImP proteins." (PMID 36746983, 2023). "Correlated expression between RARRES3 and immunoproteasome (IP) subunits (PSMB8, PSMB9 and PSMB10) observed within a BM-MSC network are conserved across datasets representing breast cancer cells and tissue." (PMID 28051153, 2017). "Our results show significant benefits, notably in terms of relapse-free survival (RFS), as well as metastasis to bones and liver, with increased expression of both PSMB8 and PSMB9 by tumor cells, particularly in the context of basal-like breast cancer and TNBC." (PMID 36746983, 2023).
breast carcinoma (continued). "Our analysis revealed no advantage to either PSMB8 or PSMB9 overexpression when considering all breast cancer subtypes together, as well as for the luminal A or luminal B subtypes specifically." (PMID 36746983, 2023). "Interestingly, while the quantities of PSMB8- or PSMB9-positive cells increased significantly with the grade of the disease, the number of immune cells remained the same for grade 1 and 2 breast cancers and decreased for grade 3." (PMID 36746983, 2023). "Furthermore, when analyzing whether CD45 and PSMB8 or PSMB9 expression were linked, we found an inverse correlation, therefore suggesting that increased ImP expression is not positively linked to immune cell infiltration in our breast cancer patient cohort." (PMID 36746983, 2023). "Our findings were similar when assessing the overall survival (OS) with high PSMB8 and PSMB9 mRNA expression being particularly important for basal-like breast cancers and important but not statistically significant for TNBC." (PMID 36746983, 2023).
autoinflammatory syndrome (6 papers, 2016 to 2025). A group of disorders of the innate immune system characterized by attacks of seemingly unprovoked inflammation without significant levels of either autoantibodies or autoreactive T cells more characteristic of autoimmune disease. "Conversely, others have identified PSMB8 (i.e. β5i) loss-of-function mutations as disease-causing in autoinflammatory syndromes and PSMB8 knockout causing elevated inflammation in mouse models of myocarditis, Alzheimer’s disease and pancreatitis." (PMID 36936919, 2023). "Mutations found in the PSMB8 gene from autoinflammatory syndrome patients can affect the PSMB8 protein and immunoproteasome functions." (PMID 29259686, 2016). "We and the other groups have reported an autoinflammatory syndrome in which the gene for proteasome subunit beta-type 8 (PSMB8) has been altered." (PMID 29259686, 2016).
colon cancer (6 papers, 2012 to 2021). "PSMB8 was significantly downregulated in 8/8 colon cancer cell lines compared to normal colon." (PMID 28622390, 2017).
leukemia (6 papers, 2017 to 2025). A malignant (clonal) hematologic disorder, involving hematopoietic stem cells and characterized by the presence of primitive or atypical myeloid or lymphoid cells in the bone marrow and the blood. "Mechanistically, PSMs have been shown to promote differentiation (PSMD4) and proliferation (PSMB8) of leukemia cell lines through the nuclear factor kappa–B (NF–κB) and the phosphatidylinositol 3–kinase (PI3K)/protein kinase B (AKT) pathways." (PMID 39335660, 2024). "Here, we provide first evidence, that inactivation of catalytic immunoproteasome subunit PSMB8 results in impaired cellular proliferation of KMT2A-r leukemia." (PMID 38049829, 2023). "Taken together, pharmacologic immunoproteasome inhibition using the specific PSMB8/LMP7 inhibitor PR-957 attenuated the leukemia initiating potential of KMT2A-r AML cells in vivo." (PMID 38049829, 2023). "To study the effects of PSMB8 (murine: LMP7) inactivation on LSC self-renewal, we used established models of murine, KMT2A-fusion driven leukemia." (PMID 38049829, 2023). "Combined targeting of PSMB8 and Menin leads to synergistic anti-proliferative effects, eradicates KMT2A-r leukemia in patient-derived xenografts and prevents development of Menin-inhibitor resistance in AML." (PMID 38049829, 2023). "Critically, PSMB8 was responsible for the self-renewal capacity of leukemia stem cells and the initiation of MLL-rearranged leukemia by regulating the DNA binding with brain abundant membrane attached signal protein 1 (BASP1), positioning it as a promising target for anti-leukemia therapy." (PMID 39335660, 2024). "Although a recent study revealed that the immunoproteasome subunit PSMB8 maintains oncogenic gene expression in KMT2A complex-driven leukemia, we first found that the increased PSMB10 but not PSMB8 is involved in chemotherapeutic drug-resistant LSC maintenance via senescent and immune regulation." (PMID 40462177, 2025).
lung carcinoma (6 papers, 2016 to 2025). "As described, NFκB, mTOR, and STAT1 have been shown to regulate the expression of PSMB8 in colon and lung cancer." (PMID 34944095, 2021).
prostate carcinoma (6 papers, 2014 to 2025). A carcinoma that arises from epithelial cells of the prostate gland. "miR-451a, identified as a regulator of the progression of several cancers, was investigated in association with PSMB8 in prostate cancer." (PMID 36430249, 2022). "PSMB8 has been reported to be a direct target of miR-451a in both PTC and prostate cancer (PCa) with evidence from luciferase activity reporter assay." (PMID 40334200, 2025). "In this study, we found that PSMB8 was targeted by miR-451a to promote ATC cell proliferation, similar results were found in prostate cancer." (PMID 37974228, 2023).
type 1 diabetes (6 papers, 2009 to 2023). "PSMB8 was found to be associated with insulin-dependent Diabetic Mellitus." (PMID 35889263, 2022). "Furthermore, high expression of PSMB8 was associated with metabolic syndromes, such as type I diabetes mellitus (NES = − 2.3, NOM P < 0.05)." (PMID 34650125, 2021). "A genomic polymorphism (G/T-37360) in PSMB8 was strongly associated with type 1 diabetes mellitus (T1DM) in an investigation of 198 unrelated T1DM Caucasian patients and 192 normal Caucasian controls from the southeastern United States." (PMID 24490108, 2013). "While these effects may be beneficial in type 1 diabetes, a recent study showed that the use of ONX-914, a PSMB8 inhibitor, exacerbated beta cell apoptosis during inflammation." (PMID 37581620, 2023).
asthma (5 papers, 2020 to 2022). "Five genes previously reported in a genome-wide association study (GWAS) on asthma, including TSLP, SLC9A4, PSMB8, IGSF5, and IKZF4 were demonstrated association in the asthma vs. control analysis." (PMID 35524249, 2022).
ischemic stroke (5 papers, 2015 to 2024). A stroke disorder caused by obstruction of blood flow to the brain, due to thrombotic (local blood clot formation) or embolic (due to a blood clot or other material traveling from another site) event. "CUX2 has been reported to be associated with atrial fibrillation in Japanese populations and also as a risk factor for ischemic stroke, while PSMB8 is a component of immunoproteasome LMP7, which is elevated in ischemic stroke and contributes to neuroinflammation." (PMID 35328807, 2022).
lymph node metastasis (5 papers, 2012 to 2025). "Patients with high PSMB8 expression showed a higher incidence of lymph node metastasis (χ2 = 10.65, P < 0.005) and extrathyroidal extension (χ2 = 8.51, P < 0.005)." (PMID 40334200, 2025). "Significant upregulation of PSMB8 was observed in the lymph node metastasis subgroup and the extrathyroidal extension subgroup." (PMID 40334200, 2025). "However, PSMB8 expression was significantly upregulated in patients with lymph node metastasis and extrathyroidal extension." (PMID 40334200, 2025). "Strong nuclear expression of PSMB8 and PBK significantly correlated with increased depth of invasion and lymph node metastasis, respectively." (PMID 26894977, 2016).
ovarian carcinoma (5 papers, 2017 to 2021). A malignant neoplasm originating from the surface ovarian epithelium. "Eight immune factors (IFT57, MAL, ANXA4, SCRN1, LTBR, KIFAP3, HSPA5, and LTN1) were positively correlated with poor prognosis of ovarian cancer, whereas six immune factors (PSMB9, FOXJ1, CTSH, MIF, CTSD, and PSMB8) were negatively correlated with poor prognosis of ovarian cancer." (PMID 34109184, 2021). "Treatment of cancer cells with 5-AC also leads to significant re-expression of B2M, CALR, CD58, PSMB8, and PSMB9 at both the RNA and protein level in the colon and ovarian cancer cell lines." (PMID 28622390, 2017). "High expression of PSMB8 and PSMB9 is related to the five-year survival of ovarian cancer." (PMID 34109184, 2021). "We confirm that treatment with DNMT inhibitors upregulates expression of the antigen processing and presentation molecules B2M, CALR, CD58, PSMB8, PSMB9 at the RNA and protein level in a wider range of colon and ovarian cancer cell lines and treatment time points than had been described previously." (PMID 28622390, 2017).
Sepsis (5 papers, 2014 to 2025). Sepsis is defined as life-threatening organ dysfunction caused by a dysregulated host response to infection. "Knocking down proteasome subunit beta type-8 (PSMB8) can inhibit the phosphorylation and degradation of IκBα, blocking the NF-κB pathway and thus reducing kidney inflammation and damage caused by sepsis." (PMID 40989844, 2025). "MICB, PSMB2, PSMB8 and PSME2 showed consistently low level of expression in melioidosis cohort irrespective of other factors like comorbidities (risk factors), duration of clinical symptoms and antibiotic treatment, compared to other sepsis controls." (PMID 28628607, 2017). "MICB, PSMB2, PSMB8 and PSME2 were significantly up regulated in other sepsis cases compared to healthy controls while these target genes showed no significant differential expression in patients suffering from melioidosis compared to healthy controls." (PMID 28628607, 2017). "Furthermore, muscle biopsies from healthy donors after IL-6 infusion (GSE10685) or patients with sepsis induced multiple organ failure (GSE13205) did not reveal any increase of the immunoproteasome expression, indicating that expression of PSMB8/-9 in muscle is specific for IIM." (PMID 25098831, 2014).
thyroid cancer (5 papers, 2019 to 2025). "Elevated PSMB8 expression may enhance the presentation of thyroid cancer-associated antigens, thereby contributing to a more effective cytotoxic T cell response." (PMID 40334200, 2025). "In thyroid carcinoma, PSMB8 is significantly upregulated, and its higher expression correlates with lymph node metastasis, extrathyroidal extension, increased immune infiltration/checkpoint expression, and a favorable prognosis." (PMID 41293269, 2025). "PSMB8 upregulation correlated with immune infiltration, checkpoint expression, and favorable prognosis in thyroid carcinoma." (PMID 41293269, 2025). "Expression profile data from The Cancer Genome Atlas showed that the expression level of PSMB8 is higher in thyroid cancer tissues than paracancerous tissues." (PMID 31559672, 2019). "In addition to transcriptional and cytokine control of PSMB8 in cancer, regulation of PSMB8 has been reported through microRNAs, with miR-451a shown to target PSMB8 in prostate and thyroid cancer to prevent tumor cell proliferation and invasion." (PMID 34944095, 2021). "We further investigated the expression profile of PSMB8 in thyroid cancer." (PMID 31559672, 2019). "Despite its significance, the contributory role of PSMB8 in oncogenesis, particularly in thyroid carcinoma (THCA), has not been well-characterized." (PMID 40334200, 2025). "Finally, to find prognostic makers of THCA, we performed survival correlation analysis on all genes in samples of thyroid cancer patients, and finally determined five hub genes based on the log-rank value: CD47, CILP, DERA, KLHL33, PSMB8." (PMID 34376710, 2021).
Arthritis (4 papers, 2015 to 2019). Inflammation of a joint. "The inhibition of PSMB8 reduces the production of inflammatory cytokines and attenuates the progression of experimental arthritis." (PMID 30682859, 2019).